CD44 (CD44 molecule (IN blood group))
Diseases named in the same sentence as CD44 in open-access papers (continued):
Sharing a sentence is not in itself a finding about the gene and the disease.
breast carcinoma (continued). "In breast cancer, combination of CD44 expression with that of alcohol dehydrogenase (ALDH), which is also expressed in hematopoietic progenitor cells, could further refine the tumorigenic population." (PMID 27457474, 2016). "Thus, the ability to identify specific CD44 isoforms that contribute to the progression of breast cancers offers a potential prognostic and therapeutic target in such tumors." (PMID 27379207, 2016). "Moreover, treatment with either a WNT5A agonist or a monoclonal antibody against CD44 in mouse breast cancer models impaired tumor progression, which suggests a therapeutic possibility." (PMID 27623766, 2016). "Moreover, the direct interaction between PrPC and CD44 is determinant for the multi-drug resistant phenotype in breast cancer cells." (PMID 27229535, 2016). "The population of CD44+/CD24−/low has emerged as one of the key markers for isolated breast cancer stem cell, which have been reported to be associated with secondary metastasis and resistance to radiotherapy on breast cancer tissues." (PMID 27313840, 2016). "This hypothesis was further corroborated by the correlation between AurkA and CD44, a marker for breast cancer stem cells (Pvalue = 0.00001) in 26 out 32 breast cancer samples." (PMID 27341528, 2016). "Moreover, disseminated tumor cells in the bone marrow of breast cancer patients were shown to be enriched with CD44+/24- cells." (PMID 27768764, 2016). "In addition to being a CSC marker, CD44+ cells were identified as CSCs in breast cancer, and were later discovered to have similar properties in HNSCC." (PMID 26907349, 2016). "The MCF7/C6 cells with gained radiation resistance after a long term treatment with fractionated ionizing radiation were derived from human breast cancer MCF7 cell line, and are enriched with cells expressing putative breast cancer stem cell biomarker CD44+/CD24-/low/ALDH+." (PMID 27036550, 2016). "Al-Hajj and colleagues were the first to show that a subpopulation of breast cancer cells, defined by a CD44+/ESA+/CD24lo cell surface phenotype, was capable of recapitulating the original tumour phenotype when transplanted into nonobese diabetic/severe combined immunodeficient (NOD/SCID) mice." (PMID 26880941, 2016). "We analyzed the CD44+ /CD24− subpopulation in five breast cancer cell lines by flow cytometry." (PMID 27302409, 2016). "Moreover, several studies have shown that IL-6/STAT3 signaling is required for the growth of CD44+CD24− stem-cell-like breast cancer cells and for the dynamic equilibrium of breast CSCs." (PMID 27609180, 2016). "What is more, NC could inhibit cellular CSCs-like self-renewal capacity of breast cancer by inhibiting the expression of pluripotency maintaining transcription factors (Nanog, Nestin and Oct-4) and CSCs markers (CD44) as well as the components of Hh pathway." (PMID 27313840, 2016). "Similar findings of CD44+ breast cancer cells show a chemoresistance as well." (PMID 26907349, 2016). "Next, we explored whether MFB treatment significantly inhibited the population of breast cancer cells that were CD44+CD24−/low, which is a feature of breast CSCs." (PMID 27223262, 2016). "Cells expressing the biomarkers of breast cancer stem cells (BCSCs; e,g., CD44+/CD24-/low/ALDH+) were further sorted and confirmed in one of these clones (MCF7/C6), indicating that BCSCs can survive long-term fractionated radiation and be responsible tumor repopulation with radiation resistance." (PMID 27036550, 2016). "To this end, we have previously reported that acquired tamoxifen resistance in breast cancer is accompanied by the overexpression of the CD44 transmembrane receptor protein that appears to contribute to their aggressive phenotype through modulation of growth factor receptor signaling." (PMID 27379207, 2016).
breast carcinoma (continued). "Our study reveals that human platelets activated by Cat K-tumor cells with epithelial-mesenchymal-like transition phenotype predominantly up-regulate SHH, PTHrP, TGFβ, Src, OPN, CD44, and P-selectin, and impact the malignancy of breast cancer cells possibly contributing to their tropism to bones." (PMID 26931461, 2016). "MMP9 was found by others to be implicated in promoting breast cancer cell migration and invasion through interactions with integrins and non-integrin type receptors such as CD44." (PMID 27042827, 2016). "We correlated the SAGE database expression patterns with our list of neurogenes to identify neurogenes that are differentially expressed in breast cancer tissue compared with healthy epithelium and that are differentially expressed in each cell subtype (CD44+ vs. CD24+)." (PMID 26673618, 2016). "The CD44+/24–/low cell population also showed the properties of self renewal and multi-lineage differentiation as well and thus, this phenotype of CD44+/24–was tagged as the putative breast cancer stem cell phenotype." (PMID 27229859, 2016). "Our data showed that CD74 interacted with CD44 in breast cancer cells." (PMID 27626171, 2016). "An additional study showed that CD44 knockdown causes breast cancer stem cells (BCSCs) to differentiate into non-BCSCs with lower tumorigenic potential, and CD44 knockdown BCSCs extended S phase similar to non-BCSCs." (PMID 27028863, 2016). "One study demonstrated that Foxp3 inhibited breast cancer cell adhesion, invasion and metastasis, while study on the molecular mechanism revealed that Foxp3 inhibited breast cancer metastasis by down-regulating CD44 expression directly." (PMID 27457382, 2016). "Similarly, hnRNP M is involved in breast cancer where it activates the switch of alternative splicing, thereby precisely controlling CD44 splice isoforms, leading to epithelial–mesenchymal transition (EMT)." (PMID 27215579, 2016). "CD44 was reported to regulate breast cancer invasion and migration." (PMID 27626171, 2016). "The expression of the following CSC markers were evaluated: CD44+/CD24low/− and EpCAMneg/low/CD49fhigh/+; shown to be expressed by stem cells of normal and cancerous human breast tissue and breast cancer cell lines and ALDH1 activity, a surrogate marker for stem cells." (PMID 27655685, 2016). "Asp-UA can efficiently down-regulate the expression of CD44 in breast cancer cells." (PMID 27683033, 2016). "Finally, we detected elevated levels of CD44 expression in breast carcinoma cells co-cultured with washed platelets activated by Cat K. Consequently, we observed an increased P-selectin expression in human platelets (p ≤ 0.01)." (PMID 26931461, 2016). "By targeting CD44, these stem-like subpopulations in breast cancers can be eliminated by a treatment that is not susceptible to drug resistance and induces catastrophic cell death only when CD44-IR700 bound to the CD44 receptor is exposed to NIR irradiation." (PMID 27302409, 2016). "Moreover, knocking down CD44 in breast cancer cells using siRNA impaired cell migration and invasion." (PMID 27623766, 2016). "Similarly, only CD44+/24- cells from breast cancer cell lines were able to form lung metastases in the in vivo experiments of another study." (PMID 27768764, 2016). "Interestingly, we found that breast cancer samples, overexpressing AurkA (>1.5 fold-change in comparison with normal breast), similarly showed increased levels of CD44 as revealed by Q-PCR." (PMID 27341528, 2016). "The existence of CSCs in breast cancer was first brought to light when it was found that the CD44+CD24−/lowLin− cells from breast cancer patients were able to generate tumors more efficiently than CD44+CD24+Lin− cells when implanted into the mammary fat pads of NOD/SCID mice." (PMID 27229859, 2016). "Interestingly, ezrin has been found in a molecular complex with CD44, Hsp90 and ErbB2 in mammary carcinoma cells." (PMID 27029001, 2016).
breast carcinoma (continued). "Similarly, this group also validated the 3′UTR of CD44 as a ceRNA for several transcripts in breast carcinoma cell lines." (PMID 26872371, 2016). "However, it was recently proposed that there are two distinct CSC sub-populations in breast cancer, one identified as CD44+/CD24low/− and the other as ALDH1+." (PMID 27835603, 2016). "Because mammary tumor cells showed the highest ratio of resistance to vincristine treatment, we treated T47D cells with vincristine and subjected them to flow cytometry analysis to detect the population of CD44+/CD24− cells." (PMID 27613838, 2016). "Moreover, CD44 is also expressed by breast cancer stem cells which can lie in a dormant state in the BM and then directly induce bone metastasis." (PMID 26064994, 2015). "A previous study demonstrated that the number of mammospheres generated was an indirect measure of mammary stem cell self-renewal; mammosphere size was representative of progenitor cell proliferation; and that the CD44+/CD24− population of breast cancer cells display characteristics of stem cells." (PMID 25586771, 2015). "Furthermore, MDA-MB-231 breast cancer cells express high level of breast cancer stem cell marker CD44 at the cell membrane and has been used as a triple negative and stem-like breast cancer cell model." (PMID 26420420, 2015). "Specifically, CD44 and ALDH1, two important breast CSC markers, increased 2- to 17-fold in all cell lines examined, suggesting that TLR3 activation, but not TLR5, 7, and 8, associates with CSC properties in different subtypes of breast cancer cells." (PMID 25257174, 2015). "Furthermore, we and others have detected elevation of CD44 in the poor prognostic basal subtype of breast cancer or stem-like tumor cells that have disseminated to the bone marrow." (PMID 26447611, 2015). "Notably, the CD44+/CD24− subpopulation in breast cancer cells is enriched under suspension sphere culture conditions." (PMID 26202299, 2015). "In addition, it has been demonstrated that serum CD44 v5 and v6 are released by breast cancer cells and increased CD44 v6 serum levels are preferentially detected in patients with liver metastases." (PMID 25885919, 2015). "For example, CD44 in breast cancer cells, neuroblastomas and prostate cancer may act as a metastatic suppressor gene, suggesting that the growth promoting pathways in these tumors are independent of CD44." (PMID 25999946, 2015). "Moreover, breast cancer cells expressing high levels of CD44 and low levels of CD24 maintain stemness properties." (PMID 25885919, 2015). "CD24− and CD44+ cells have been putatively identified as breast cancer stem cells." (PMID 26694341, 2015). "Importantly, the downregulation of miR-200a, b, and c has been observed in CSC-like (CD44+/CD24−) cells of breast cancer." (PMID 26064420, 2015). "In addition, different expression levels of CD44 have been reported in other types of tumours, including colon, ovarian, and breast cancers." (PMID 25881239, 2015). "Furthermore, the CD44+CD24− phenotype correlated more closely with basal phenotype than with tumorigenicity in breast cancer cell lines." (PMID 25497455, 2015). "Alternative splicing and variation in N- and O-glycosylation give rise to the various CD44 isoforms distinguishable by their differential roles in breast cancer CD44s, one of the most expressed CD44 isoforms, is up-regulated in primary tumors but correlates with overall patient survival." (PMID 25629807, 2015). "Tissue CD24 expression levels may help to predict survival in patients with breast cancer, but studies show that highly invasive breast cancer cells often express CD44+/CD24−." (PMID 25511546, 2015). "The CD44+/CD24−/low cells are a subset of breast cancer stem cells (BCSCs)." (PMID 26472025, 2015). "Similarly, MS from breast cancer tissues have been shown to proliferate in vitro and generate tubule-alveolar structures composed of CD44+/CD24− cells." (PMID 25881039, 2015).
breast carcinoma (continued). "Furthermore, CD44-positive, stem-like breast cancer cells have been detected within the bone marrow of early-stage breast cancer patients." (PMID 26447611, 2015). "The results indicate high CD44 expression on both breast cancer tissues and normal control tissues." (PMID 25909172, 2015). "In addition, mice with high CD44 expression and active breast cancer cells displayed smaller tumor volumes and increased cellular necrosis after HA-Lipid-PTX treatment, suggesting it is a considerably more effective treatment strategy." (PMID 25909172, 2015). "CD24 and CD44 surface staining was used to estimate the CSC population of breast cancer cells." (PMID 26522589, 2015). "In the case of breast cancer, there remains a need to determine whether CD44+CD24−ESA+ cells are true breast CSCs across various breast cancer subtypes." (PMID 25905435, 2015). "CD44 expression is selectively over-expressed in estrogen receptor (ER)- and progesterone receptor (PR)-negative breast tumors, with enrichment detected in basal-like breast cancer (BLBC)." (PMID 26447611, 2015). "Some studies showed a protumorigenic role for CD44, while others showed a protective role for CD44 in breast cancer, suggesting that CD44 may influence tumor growth or metastasis differently at different phases of tumor progression." (PMID 26504780, 2015). "Human breast cancer cell lines also differ quantitatively in the proportion of CD44+CD24− cells." (PMID 25905435, 2015). "Furthermore CD44-expressing breast cancer cells with stem-like characteristics have been detected within the bone marrow of breast cancer patients presenting with early-stage disease." (PMID 25888636, 2015). "Interestingly, CD44 positive, “stem-like” breast cancer cells have been detected within the bone marrow during early stage disease." (PMID 25888636, 2015). "The observed expansion of CD44+CD24−/lowESA+ cells by hypoxia encouraged us to examine whether oxygen levels affected the proportion of different subpopulations of CSCs in breast cancer cells." (PMID 26372732, 2015). "Similarly, label-retaining cells (LRC) with self-renewal ability have been identified in a sub-population of CD44+/CD24-/ESA+ breast cancer cells, and these cells were endowed with resistance to chemotherapy." (PMID 26318423, 2015). "Combining EGFR inhibitors with CD44 inhibitors may be a novel method for breast cancer treatment, especially TNBC." (PMID 25429827, 2015). "Indeed, miR-7 modulates the histone methyl transferase SETDB1, regulating a STAT3-dependent EMT, and acquisition of SC traits in CD44+ cells derived from MDA-MB-231 human breast cancer cells." (PMID 25774169, 2015). "Also, IL-6 is capable of generating CD44+ cells with stem-like properties through induction of the EMT in the T47D breast cancer cell line." (PMID 25590298, 2015). "nCaPCMHA-AF488 was taken up by CD44+/CD24− BT-474EMT breast cancer cells within 18 hours." (PMID 26448751, 2015). "Therefore, CD44+CD24−/lowESA+ is a potential breast CSC marker for further investigation of this group of breast cancer cells with tumorigenic properties." (PMID 25905435, 2015). "However, Kim and colleagues reported that the CD44+/CD24− group is considered a favorable prognostic subgroup in breast cancer." (PMID 25429827, 2015). "First, FACS analysis of CD44, a well-recognized marker of breast cancer stem cells, demonstrated that MPA induced a large and highly reproducible CD44+ shift in T47-D cells, suggesting that MPA induces an increase in stem cell- or progenitor-like cells, as previously shown." (PMID 26312209, 2015). "Our findings indicate that breast cancer cells with a hyperactive AF1q/TCF7/CD44 regulatory axis in the primary sites may represent “metastatic founder cells” which have invasive properties." (PMID 26079538, 2015).
breast carcinoma (continued). "Human breast cancer cell lines (MDA-MB-468, BT-549, and Hs578T) were characterized by the appearance of several bands on agarose gel electrophoretograms when examining the CD44 variant region with a primer pair spanning the entire variant region." (PMID 25909172, 2015). "Secreted RHAMM can bind HA and, in concert with CD44, augment invasiveness in breast cancer." (PMID 25999946, 2015). "Since CD44+/CD24− were widely used as a cell surface marker of CSCs, we next detected the expression of CD44+/CD24− in breast cancer cells treated with morphine (10 μM) and found that the CD44+/CD24− proportion were increased from 47.87 ± 1.01% to 68.8 ± 2.68% in BT549 cells." (PMID 25686831, 2015). "Thus, IL-6 is capable of generating CD44+ cells with stem-like properties through induction of EMT in the epithelial-like T47D breast cancer cells." (PMID 25590298, 2015). "Moreover, CD44, a stem cell marker for breast cancer, has also been demonstrated to be responsible for the resistance to cytotoxic drugs." (PMID 26090664, 2015). "In addition, a study of breast cancer reported that the EMT traits parallel the CSC phenotype in which CD44 is highly expressed." (PMID 25797261, 2015). "To further confirm that the two activation states of CD44 are differentially located, we assessed CD44 expression and fl-HA binding activity on four breast cancer cell lines (MDA-MB-231, MDA-MB-468, BT-549, and Hs578T) and four normal cell lines (PBMCs, NIH3T3, CV-1, and NFs)." (PMID 25909172, 2015). "CD44’s affiliation with lipid rafts is likely to occur through its palmitoylation, which may play a role in breast cancer malignancy." (PMID 26347743, 2015). "Accordingly, targeting CSCs could represent a promising therapeutic strategy for TNBC, a notion supported by the fact that these tumors have the highest percentage of CD44-positive CSCs compared to the other breast cancer subtypes." (PMID 26011941, 2015). "Importantly, specific downregulation of PD-L1 in claudin-low breast cancer cells showed signs of EMT reversal as manifested by CD44 and Vimentin downregulation and CD24 upregulation." (PMID 26245467, 2015). "In the previous cases (with and without treatments), we have considered that metastases in the bone are originated only by breast cancer cells with four driver mutations relative to four proteins EPCAM, CD44, CD47 and MET, and they correspond to four branching of the CTCs departing from the DLU." (PMID 25978366, 2015). "Next, to prove the tumor origin of DAPI−/CD45−/EpCAM-negative/CD24−/CD44+/uPAR/int β1 cells as putative CTCs, we performed transcriptome analysis of 83 breast cancer candidate genes present in human breast cancer real-time PCR (RT2-PCR) profiler arrays (Qiagen)." (PMID 26631983, 2015). "CD44, a cell-surface glycoprotein, is highly expressed in tumors, especially in breast cancer." (PMID 25909172, 2015). "Taken together, the present study suggested that the modification of GSN expression might involve in the TGF-β1 signaling events for inducing cancer cell stemness and increasing cell migration and invasion in CD44+/CD24- subpopulation of breast cancer cells." (PMID 26482896, 2015). "It shows that highly aggressive basal-type breast cancer cell lines are characterized by both the high expressions of mesenchymal markers including TGFB1 and the markers associated with cancer stem-like features (CD44+/CD24−)." (PMID 26462028, 2015). "Flow cytometric analysis of breast cancer spheroids treated with 40 μM 6-shogaol for 18 hours showed that the percentage of cells characterized by CD44+CD24-/low were substantially less in the treated spheroids when compared to the untreated ones (2.3% vs. 27.3%)." (PMID 26355461, 2015). "Further analyses revealed that miR-21 is regulated by an upstream promoter containing AP1 binding site(s), and chromatin immunoprecipitation (CHIP) assays demonstrated that stimulation of miR-21 expression by HA/CD44 interaction is c-Jun-dependent in these breast cancer cells." (PMID 24606718, 2014).